CDK14 (cyclin dependent kinase 14)
Diseases named in the same sentence as CDK14 in open-access papers (continued):
Sharing a sentence is not in itself a finding about the gene and the disease.
Parkinson disease (1 paper, 2025). A progressive degenerative disorder of the central nervous system characterized by loss of dopamine producing neurons in the substantia nigra and the presence of Lewy bodies in the substantia nigra and locus coeruleus. "In contrast, poor IC clock levels tracked with elevated expression of CDK14/PFTK1 (FDR = 2.77 × 10−29), a regulator of the Wnt signal transduction pathway, a proinflammatory mediator associated with Parkinson’s disease and several cancers, and sensitive to changes in diet." (PMID 40467932, 2025).
synucleinopathy (1 paper, 2024). A neurodegenerative disease that is characterized by the abnormal accumulation of aggregates of alpha-synuclein protein in neurons, nerve fibers or glial cells. "In summary, we suggest that CDK14 represents a novel therapeutic target for PD-associated synucleinopathy." (PMID 38575601, 2024). "We show that the reduction of CDK14 protein levels is well tolerated and causes a reduction in pathogenic α-Syn accumulation in murine and human models of synucleinopathy." (PMID 38575601, 2024). "Further in vivo experiments will test whether CDK14 inhibition rescues PD-like neuron loss and behavioral phenotypes in models of synucleinopathies; elucidating the potential of targeting CDK14 as a therapeutic strategy for PD patients." (PMID 38575601, 2024). "Based on these in vivo CDK14 inhibitor administration experiments, we hypothesize that blockage of CDK14 activity reduces loads of pathology-linked forms of insoluble α-Syn, potentially shifting synucleinopathy progression to an earlier phase of disease development." (PMID 38575601, 2024). "Future histopathology experiments may generate deeper insights into whether CDK14 accumulates, and forms aggregates together with α-Syn in patients with synucleinopathies." (PMID 38575601, 2024). "Importantly, the genetic reduction of CDK14 in DaNs derived from an individual with synucleinopathy shows equal promise in preventing phenotypic development." (PMID 38575601, 2024).
tumor (39 papers, 2012 to 2026). "As one of the gene regulators that were closely associated with cell proliferation and cell apoptosis, CDK14 has been shown to be related to tumor invasiveness and prognosis by a large number of studies 44-47." (PMID 32802182, 2020). "In addition, in solid tumors such as non-small cell lung cancer, colorectal cancer, gastric cancer, etc., CDK14 often plays a tumor-promoting role as an oncogenic factor and is associated with poor patient prognosis." (PMID 37599359, 2023). "Especially, CDK14 is positively associated with high-motility phenotype of tumor cells." (PMID 31824858, 2019). "Cdk14 is reported to have higher expression levels in many tumor tissues than in normal tissues, and significantly enhances the proliferation and migration of cancer cells." (PMID 39827158, 2025). "In esophageal squamous cell carcinoma, CDK14 can be used as one of the predictors of tumor prognosis and chemotherapy sensitivity." (PMID 37599359, 2023). "For example, the lncRNA, NORAD, is upregulated in non-small cell lung cancer (NSCLC) and accelerates the progression of NSCLC by enhancing tumor cell proliferation by targeting the miRNA-455/CDK14 axis." (PMID 36793900, 2023). "Further analysis showed that high expression of CDK14 was positively correlated with the high tumor stage (P = 0.026)." (PMID 37670966, 2023). "The mechanism of miR-539-3p-mediated tumorigenesis was targeted SPARCL1, RNF2, CTBP1, or CDK14 and inhibited the expression of these proteins in tumor cells." (PMID 35303885, 2022). "In conclusion, the identification of miR-1825 as a tumor suppressive miRNA in human GBM that acts by targeting CDK14 provides additional evidence of a pivotal role for miRNAs in GBM progression." (PMID 32605563, 2020). "The upregulated expression of CDK14 promotes tumor cell proliferation, migration and invasion through Wnt/β— catenin signaling pathway in breast cancer." (PMID 31534156, 2019). "Gain of miR-216a can inhibit tumor cells proliferation, migration and invasion in vitro and in vivo via suppressing the expression of CDK14." (PMID 31798627, 2019). "CDK14 has been reported to act as a Cyclin Y-dependent protein kinase and promote tumor progression." (PMID 31824858, 2019). "As miR-216a/CDK14 axis modulated OS tumour invasiveness, we thus sought to explore the effects of miR-216a/CDK14 axis on the E-cadherin and N-cadherin production in mice." (PMID 29022909, 2017). "The results showed that the level of CDK14 was closely correlated with tumour size and histological grade." (PMID 29022909, 2017). "Briefly, the miR-216a-expressing group had a lower number of tumour foci in the lungs than the control group, whereas the miR-216a plus CDK14 group displayed reversal of the effects of miR-216a on the metastatic foci." (PMID 29022909, 2017). "Therefore, it is a feasible strategy to use CDK14 as a therapeutic target and inhibit tumors in some Cdk14 overexpressed tumor types." (PMID 39827158, 2025). "In addition, the lncRNA Neat1 was reported to regulate CDK6 and CDK14 via sponging miR107 and further promote tumor growth." (PMID 35501920, 2022). "In addition, tumours in mice inoculated with miR-216a-overexpressing 143B cells had decreased expression of CDK14 and EMT markers." (PMID 29022909, 2017). "To date, studies have indicated that CDK14 depletion impairs tumour angiogenesis." (PMID 29022909, 2017). "Moreover, tumours in mice formed by miR-216a plus CDK14-overexpressing 143B cells showed a reversal of the miR-216a effect on tumour growth." (PMID 29022909, 2017). "Armed with the genetic evidence of mutations involving KRAS and CDK6/CDK14 as well as the response to single agent therapies, we reasoned that treatment with a combination of drugs addressing the key mutations associated with propagation and metastasis in the CB42 should result in tumor regression." (PMID 25162504, 2014).
tumor (continued). "By silencing the function of Cdk14, the inhibitory effect of miR-198/E2F2 can be weakened, thereby achieving the purpose of tumor treatment." (PMID 39827158, 2025). "CDK14 has been implicated in pathobiology of many cancers, including liver, ovarian, breast, gastric, pancreatic, esophageal, glioblastoma and osteosarcoma, although most of these studies derived from the analyses of cell lines rather than strong evidences from primary tumor samples." (PMID 39800748, 2025). "The canonical Wnt signaling pathway is activated by the mitotic CDK14/cyclin Y complex via phosphorylation of the LRP6 coreceptor, which leads to anti-inflammatory signaling that inhibits tumor growth." (PMID 37258567, 2023). "Consistently with transcriptomic analysis, we also observed marked differences in the mRNA levels of BAX, HRK, CDK6, CDK14, and BCL2 between the sgCONT and NOXAKO tumor cells after co-incubated with CD19 CAR T cells." (PMID 35370290, 2022). "To test the importance for tumor growth and metastasis of these genes we introduced inducible cDNAs of CDK6, CDK14 and Fzd6 alone or in combination into the parental ES cell line of the β-Catenin driven model, 91C5, and generated chimeric mice." (PMID 25162504, 2014). "We also found that putative tumor suppressors, such as FOXP1, STK4, and ATM were frequently hypermethylated and silenced whereas oncogenes, such as UHRF1, MPZL1, CDK14, RACGAP1, and RAB13, were hypomethylated and overexpressed suggesting that DNA methylation changes contribute to PTCL development." (PMID 38464090, 2024). "None of the new chimeric mice showed accelerated tumorigenesis or higher incidence of tumors, yet 3 of 4 tumors harboring CDK14 or CDK14/CDK6/FZD1 were easily propagated, strongly suggesting that overexpression of CDK6 and CDK14 are important for ectopic tumor growth and metastasis." (PMID 25162504, 2014). "Comparison of the genome of this tumor, CB42, with genomes from non-propagating tumors by array CGH and sequencing revealed an amplicon on chromosome five containing CDK6 and CDK14, and a KRAS mutation, respectively." (PMID 25162504, 2014). "Few notions are available on the possible role of CDK14 and CDK15 in cancer progression showing some degree of variability among the different tumors and or the different studies resulting in a still unclear picture of their possible involvement in tumor progression." (PMID 39800748, 2025). "Previous studies based on parallel exome sequencing of HBsAg-seropositive HCC, observed that the virus-affected genes including VCAM1 and CDK14 only presented in PVTT but not in the primary tumor, suggesting that genes perturbed by viral integration may contribute to tumor invasive capacity." (PMID 31200735, 2019).
cancer (32 papers, 2012 to 2025). A tumor composed of atypical neoplastic, often pleomorphic cells that invade other tissues. "Inhibition of the N7-methylguanosine modifying enzyme METTL1 delayed cancer cell migration and invasive activity due to Cdk14 overexpression." (PMID 39827158, 2025). "Overexpressed CDK14 has been reported in many cancers, including breast 13, gastric 14, non-small cell lung 15, and ovarian 16 cancers." (PMID 37670966, 2023). "KEGG analysis showed that CDK14-correlated (positively or negatively) genes gathered at the pathways of chemoresistance, transcriptional misregulation in cancer, etc." (PMID 37670966, 2023). "Our GSEA analysis in pan-cancer from the TCGA database showed that CDK14 expression was correlated with the TGF-β signaling pathway in OC." (PMID 37670966, 2023). "To explore the regulatory mechanism of CDK14 expression, we analyzed the CDK14-related signaling pathways in pan-cancer from the TCGA database." (PMID 37670966, 2023). "While much more remains to be learned about the regulation and activity of CDK14 in OS and other cancers, current evidence suggests CDK14 is a driver of OS pathogenesis." (PMID 32344731, 2020). "Other candidates, such as the SPTBN1, NSD3 and CDK14 genes, are able to influence cancer progression through Wnt signaling." (PMID 30102725, 2018). "As an activator of the WNT pathway through mediating the phosphorylation of LRP6 in the G2/M phase, CDK14 was found that it could promote the progression of several cancers." (PMID 35479936, 2022). "However, the circRNAs derived from CDK14 as well as their function in cancer progression are still poor understood." (PMID 35002529, 2022). "MiR-26b directly inactivates cyclin-dependent kinase CDK14 in cancers." (PMID 35570840, 2022). "CDK14 was reported to be involved in the progression of various cancers, including OC." (PMID 32377170, 2020). "Furthermore, CDK14, CDK16, CDK18 and cyclin Y have all been linked to cancer cell proliferation, migration or cancer drug resistance." (PMID 28057719, 2017). "In HCC, miR-877-5p could decrease cancer cell invasion, migration, and growth via targeting CDK14." (PMID 33407443, 2021). "We also analyzed a panel of putative cancer-related genes, including CDK8, MITF, SMAD7, KLF12, AG02, CDK14, and BCL-9, but only PTEN expression was shown to be significantly altered by miR-216a overexpression." (PMID 30061175, 2018). "Notably, it stabilizes oncogene mRNAs, such as Cyclin-Dependent Kinase 14 (CDK14), which accelerates cancer cell proliferation." (PMID 40809384, 2025). "The combined analysis of RNA-seq and ChIP-seq for H2A.Z showed downstream gene regulation to mainly occur via the transcriptional misregulation in the cancer pathway, its target genes mainly including TCF3 CDK14, JUP, SPINT1, CDKN1A, and IGF1, each of which corresponded to different cell phenotypes." (PMID 34120148, 2021). "Previous studies have identified that CDK14 and ANKRD9 are correlated with cancer." (PMID 32649035, 2020). "An intestinal immune network for IgA production might provide new markers in enteric DLBCL, such as CCR10, TNFRSF13B, AICDA, and HLA-DOB, as well as genes involved in transcriptional misregulation in cancer (NFKBIZ, FUT8, LMO2, CCND2, BCL2A1, ETV6, and CDK14)." (PMID 29992138, 2018). "In addition, we found that acetylation of H2A.Z in HCC could change the chromatin status and promote the transcription of downstream genes, including TCF3, CDK14, JUP, SPINT1, CDKN1A, and IGF1, which are important regulatory molecules in the cancer misregulation pathway." (PMID 34120148, 2021).
infection (2 papers, 2023 to 2025). The state of being infected such as from the introduction of a foreign agent such as serum, vaccine, antigenic substance or organism. "We found that the CDK14 protein was detectable in the cytoplasm rather than in the nucleus in SK3R-PTX and OV3R-PTX cells after infection with the CDK14-shRNA virus." (PMID 37670966, 2023). "To achieve this, we constructed shRNAs targeting human CDK14 gene and transfected the HUVEC and A549 via lentivirus-mediated infection." (PMID 39827158, 2025).
hematologic malignancies (1 paper, 2024). "CDK14’s role in hematologic malignancies is relatively unexplored, especially compared to typical CDKs." (PMID 38438856, 2024).
CDK14 also shares sentences with these, for which no sentence is quoted: esophageal cancer (3 papers); B-cell lymphomas (2); leukemia (2); oesophageal cancer (2); pancreatic ductal adenocarcinoma (2); bladder cancer (1); cognitive decline (1); gastric tumor (1); invasive ductal carcinoma (1); metastatic tumors (1); nasopharyngeal carcinoma (1); neuropathy (1).